ATP8B2 (ATPase phospholipid transporting 8B2)
Description:
Catalytic component of P4-ATPase flippase complex, which catalyzes the hydrolysis of ATP coupled to the transport of phosphatidylcholine (PC) from the outer to the inner leaflet of the plasma membrane. May contribute to the maintenance of membrane lipid asymmetry.
Synonyms: ATPID; KIAA1137
Tractability: Antibody: UniProt places it where antibodies can reach, with high confidence; its Gene Ontology location is reachable by antibodies, with high confidence; UniProt predicts a signal peptide or a membrane-spanning region; the Human Protein Atlas places it where antibodies can reach. PROTAC: ubiquitination databases record sites on it.
Gene: Protein-coding gene on chromosome 1 (154,325,520 to 154,351,307, forward strand). Ensembl gene ENSG00000143515.
Subcellular location: Cell membrane; Endoplasmic reticulum membrane
Subcellular location (Human Protein Atlas): Plasma membrane; Cytosol; Nucleoli
Pathways (Reactome):
Transport of small molecules: Ion transport by P-type ATPases
Gene Ontology:
Molecular function: ATPase-coupled intramembrane lipid transporter activity; phosphatidylcholine flippase activity; phosphatidylcholine floppase activity; protein binding; ATP binding; ATP hydrolysis activity; magnesium ion binding; nucleotide binding
Biological process: Golgi organization; monoatomic ion transmembrane transport; phospholipid translocation; phospholipid transport
Cellular component: endoplasmic reticulum membrane; Golgi apparatus; phospholipid-translocating ATPase complex; plasma membrane; trans-Golgi network; cytoplasm; endomembrane system; membrane
Genetic constraint (gnomAD): Loss-of-function variants: 70 observed, 136.97 expected, observed/expected ratio (o/e) 0.51, 90% interval 0.42 to 0.62. The synonymous counts are far from expectation, so gnomAD's model fits this gene poorly and the ratio says little. Missense variants: 1,084 observed, 1,579.3 expected, observed/expected ratio (o/e) 0.69, 90% interval 0.65 to 0.72. Synonymous variants: 507 observed, 609.96 expected, observed/expected ratio (o/e) 0.83, 90% interval 0.77 to 0.89.
Homologues: Orthologues: chimpanzee ATP8B2 (99% identical), macaque ATP8B2 (99% identical), pig ATP8B2 (98% identical), guinea pig ATP8B2 (97% identical), mouse Atp8b2 (97% identical), rat Atp8b2 (97% identical), dog ATP8B2 (95% identical), Drosophila melanogaster CG4301 (33% identical), Drosophila melanogaster CG9981 (29% identical), Drosophila melanogaster CG31729 (27% identical), Caenorhabditis elegans tat-5 (25% identical), Caenorhabditis elegans tat-6 (25% identical). Paralogues in human: ATP8B4 (70% identical), ATP8B1 (54% identical), ATP8B3 (44% identical), ATP8A2 (39% identical), ATP8A1 (39% identical), ATP10A (37% identical), ATP10D (37% identical), ATP10B (35% identical), ATP11A (33% identical), ATP11C (33% identical), ATP11B (33% identical), ATP9B (28% identical), and 1 more.
Diseases named in the same sentence as ATP8B2 in open-access papers:
ATP8B2 is named in the same sentence as 5 diseases in open-access papers, as found by Europe PMC text mining. Sharing a sentence is not in itself a finding about the gene and the disease. The quoted sentences say what the papers report.
glaucoma (1 paper, 2026). Increased pressure in the eyeball due to obstruction of the outflow of aqueous humor. "Despite the similarity in ATP8B2 levels between control and glaucoma samples after normalization, its activity was found to be significantly reduced when compared to the control group." (PMID 41555830, 2026). "We identified a distinct set of ocular lipid species altered in glaucoma, implicating alterations in the levels and functionality of the lipid transporter ATP8B2." (PMID 41555830, 2026). "Both ATP8B2 and transmembrane protein 30A (TMEM30A) were found to decrease in glaucoma compared to control." (PMID 41555830, 2026). "However, when we normalized the samples using CD133, which also served as control, we did not observe statistically significant differences in ATP8B2 and TMEM30A levels between glaucoma and control." (PMID 41555830, 2026).
rhizomelic chondrodysplasia punctata (1 paper, 2024). Rhizomelic chondrodysplasia is a form chondrodysplasia punctata, a group of diseases in which the common characteristic is calcifications near joints at birth. "Variants within ATP8B2, a plasmalogen transporter, are associated with motor deficit progression of PD-afflicted patients, and reduced levels of plasmalogens cause a human genetic disorder, rhizomelic chondrodysplasia punctata (RCDP), characterized by severe neurological symptoms." (PMID 38382846, 2024).
cancer (2 papers, 2022 to 2023). A tumor composed of atypical neoplastic, often pleomorphic cells that invade other tissues. "Nevertheless, several different cancer cells get sensitized to evasion from ferroptosis by lowering plasmalogens where expression of ATP8B2 mRNA is increased, though both protein and mRNA expressions of AGPS and TMEM189 are reduced." (PMID 35832735, 2022). "ANKRD44 and ATP8B2 were rarely reported in any cancer research." (PMID 36973645, 2023).
tumor (2 papers, 2022 to 2023). "These included well-known receptor tyrosine kinase genes (EGFR, TEK and OSMR) that activate MAPK and PI3K signaling pathways, and other tumor-promoter genes (ATP8B2, DAAM1, SLAMF8 and SRGN) as well as tumor-suppressor genes (A2M, DAPK1, RASSF8 and SOCS3)." (PMID 37190308, 2023).
ATP8B2 also shares sentences with these, for which no sentence is quoted: pancreatic adenocarcinoma (1 paper).